IAPP (islet amyloid polypeptide)
Diseases named in the same sentence as IAPP in open-access papers (continued):
Sharing a sentence is not in itself a finding about the gene and the disease.
peripheral neuropathy (2 papers, 2023 to 2024). A disorder affecting the peripheral nervous system. "Moreover, a recent study has demonstrated IAPP oligomers in the skin of T2D patients and has provided evidence for an IAPP-driven peripheral neuropathy in a mouse model of the disease." (PMID 39062913, 2024). "We investigated whether human islet amyloid polypeptide (hIAPP), which forms pathogenic aggregates that damage pancreatic islet β cells in T2DM, is involved in T2DM-associated peripheral neuropathy." (PMID 36917177, 2023).
infection (1 paper, 2022). The state of being infected such as from the introduction of a foreign agent such as serum, vaccine, antigenic substance or organism. "Lastly, LL-37 may disrupt some of the consequences of infection, such as alpha-synuclein plaque deposition in the brain, and IAPP plaque deposition in the pancreas associated with the development of insulin insensitivity." (PMID 35634307, 2022).
IAPP also shares sentences with these, for which no sentence is quoted: Huntington disease (7 papers); prion disease (7); transmissible spongiform encephalopathies (3); atherosclerosis (2); cardiac amyloidosis (2); cardiovascular diseases (2); gout (2); inflammation (2); Parkinson (2); retinopathy (2); AA amyloidosis (1); autism spectrum disorder (1); Beckwith-Wiedemann syndrome (1); carcinoma of the thyroid (1); cataract (1); chronic pancreatitis (1); Creutzfeldt-Jakob disease (1); diabetic neuropathy (1); endocrine disorders (1); familial Alzheimer disease (1); familial amyloid polyneuropathy (1); frontotemporal dementia (1); hyperlipidemia (1); intervertebral disc degeneration (1); lipomatosis (1); metabolic syndrome (1); migraine with aura (1); multiple myeloma (1); neuroblastoma (1); neuroendocrine tumors (1).
A further 13 diseases each share a sentence with IAPP in 1 paper.